WRN (WRN RecQ like helicase)
Diseases named in the same sentence as WRN in open-access papers (continued):
Sharing a sentence is not in itself a finding about the gene and the disease.
Werner syndrome (continued). "They act in both homologous recombination initiation and in preventing aberrant exchanges, and when WRN protein lacks helicase and exonuclease activities, the cancer-prone Werner syndrome ensues, which is characterized by an increased genomic instability and reduced homologous recombination." (PMID 22720024, 2012). "A physiological effect of RecQ activity is seen in humans where deficiency in RecQ helicases WRN, BLM and RECQ4 give rise to recessive disorders Werner syndrome, Bloom syndrome and Rothmund-Thompson syndrome (as well as RAPADILINO and Baller-Geller syndromes), respectively." (PMID 22720024, 2012). "These C57BL/6N WRN helicase mutant mice did not severely age prematurely, but displayed phenotypes associated with human Werner syndrome." (PMID 21559242, 2011). "However, it has been recently shown in Xenopus laevis, that the WRN (Werner's syndrome) RecQ-like helicase also acts at the initiation step of homologous recombination in the unwinding of broken DNA ends." (PMID 18294364, 2008). "WRN gene defects can lead to Werner syndrome (WS), which is an extremely rare human recessive genetic disease characterized by highly unstable genome and chromosomal abnormalities and is associated with premature aging and a variety of cancers." (PMID 40649870, 2025). "Pathogenic mutations on BLM, WRN, and RECQL4 are associated with several pathological conditions, namely Bloom syndrome (BS), Werner syndrome (WS), and Rothmund-Thomson syndrome (RTS)." (PMID 40728512, 2025). "Moreover, homozygous point mutations that inactivate WRN helicase activity have been shown not to result in clinical manifestations of Werner syndrome, further highlighting the importance of the exonuclease function." (PMID 40261911, 2025). "In accordance with the findings in primordial dwarfism of Majewski type 2 caused by pericentrin (PCNT) mutation and in Werner syndrome caused by WRN mutation, severe insulin resistance is not congenital in these patients but appears during late childhood or adolescence." (PMID 36627765, 2023). "Mutations in WRN, BLM, and RECQL4 cause Werner syndrome (WS), Bloom syndrome (BS), and Rothmund–Thomson syndrome (RTS), respectively, which are associated with premature aging, cancer predisposition, and chromosome abnormalities." (PMID 35681785, 2022). "In the Werner syndrome (premature aging disorder), deacetylation of SIRT6-dependent histone at telomeres produces a particular chromatin condition which is essential for DNA processing in the binding of ATP-dependent helicase of Werner syndrome (WRN)." (PMID 33920726, 2021). "The Werner syndrome protein (WRN) belongs to the RecQ family of helicases and its loss of function results in the premature aging disease Werner syndrome (WS)." (PMID 33054770, 2020). "First, we examined CHK1 phosphorylation at Ser345 in an isogenic pair of uncorrected and WRN wild-type-corrected (WSWRN) SV40-transformed Werner syndrome (WS) fibroblasts, in which ATM (ATMi), ATR (ATRi) or both (ATMi/ATRi) were chemically inhibited." (PMID 30657978, 2019). "A small subset of cases of Atypical Werner syndrome (AWS) (those with some features of Werner syndrome, without mutations in WRN or altered expressions of the WRN protein) may be caused by accumulations of low levels of progerin." (PMID 30048243, 2018). "Werner Syndrome Protein (WRN), the protein mutated in WS, is unique among RecQ family proteins in that it possesses exonuclease and 3′ to 5′ helicase activities." (PMID 30400178, 2018). "Other examples are the Hutchinson-Gilford Progeria (HGP) and Werner syndrome (WS), two premature aging disorders characterized by common natural aging already in childhood and attributed to mutations in the lamin A (LMNA) and the Werner syndrome RecQ helicase like (WRN) genes." (PMID 26974671, 2016).
Werner syndrome (continued). "The best-studied PSs are Werner Syndrome (WS), Ataxia Telangiectasia (AT) and Hutchinson Gilford Progeria (HGPS), which carry causal mutations in the WRN RecQ helicase, ataxia telangiectasia checkpoint kinase ATM, and lamin A/C respectively." (PMID 25214013, 2015). "The absence of WRN protein expression in Müller cells in patients with Werner syndrome may cause the development of the CME associated with Müller cell dysfunction." (PMID 24620826, 2014). "Werner syndrome (WS), also termed “adult progeria” due to its late phenotypic onset, has been extensively investigated for its relationships with OS, and we reported the multiple involvements of the defective WRN protein both in DNA stability and in redox balance." (PMID 24876913, 2014). "This implies that the helicase deficiency from WRN mutations may not necessarily be the cause for the short stature of Werner syndrome patients." (PMID 25018888, 2014). "In addition, the role of the WRN protein in epigenetic control of pluripotent stem cell differentiation, could lead to Werner syndrome-like symptoms in this cell strain." (PMID 24799429, 2014). "WRN protein, defective in Werner syndrome (WS), a human segmental progeria, is a target of serine/threonine kinases involved in sensing DNA damage." (PMID 24429382, 2014). "Interestingly, we found that LBCs carrying a Del or Dup of 1q21.1 failed to arrest in G2 following Topo II inhibition, and instead, exhibited elevated pseudomitosis similar to WRN-defective cells from a patient with Werner syndrome (OMIM #277700), which are known to exhibit defective DCC activation." (PMID 21824431, 2011). "BLM is in a family of RecQ helicases that includes WRN and RECQL4, responsible for Werner syndrome and Rothmund-Thompson syndrome, respectively." (PMID 35359366, 2022). "Human diseases leading to premature ageing phenotypes, such as Bloom and Werner syndromes, originate from dysfunctions in two RecQ helicases involved in DNA recombination, BLM, and WRN." (PMID 25402830, 2014). "For example, genes responsible for Werner syndrome (WS), Rothmund-Thomson syndrome (RTS), Bloom syndrome (BS), and Hutchinson-Gilford progeria syndrome (HGPS) are RECQ3 (WRN), RECQL4, RECQ2, and LMNA, respectively." (PMID 25365557, 2014). "The expression of WRN proteins in Müller cells of adult human retinas indicates that WRN gene is active in Müller cells, and therefore a pathophysiological link may exist between the mutation in the WRN gene and the development of CME in patients with Werner syndrome." (PMID 24620826, 2014). "The controls were two normal primary fibroblast cultures, 82-6 and 88-1 as well as cultures of WRN mutant fibroblasts, Registry# MCI7885, derived from a patient with classical Werner syndrome." (PMID 23847654, 2013). "Werner syndrome results from the myriad effects of increased genomic instability due to lack of function of the WRN protein." (PMID 35359366, 2022). "Patients with Werner syndrome present with an increased incidence of cancer, indicating that the lack of a proper WRN function affects tumorigenesis." (PMID 32708070, 2020). "The lack of three coding genes BLM, WRN and RecQ4 leads to occur related diseases, which are Bloom syndrome (BS), Werner syndrome (WS) and Rothmund-Thomson syndrome (RTS), respectively." (PMID 31660888, 2019). "Werner syndrome cells lacking functional WRN specifically show a defect in processing stalled replication forks." (PMID 22562358, 2013). "In humans defects in three of at least five functionally non-redundant genes encoding RecQ helicases are associated with severe heritable disease, i.e. Bloom's syndrome (BLM, RECQ2, RECQL3 gene), Rothmund-Thomson syndrome (RECQL4 gene) and Werner's syndrome (WRN, RECQ3, RECQL2 gene)." (PMID 22327026, 2012).
Werner syndrome (continued). "Given that the levels of plasminogen activator inhibitor type 1 (PAI-1) were found to be significantly increased in Werner syndrome patients, is quiet possible that PAI-1 expression could be under regulation of WRN helicase." (PMID 18312663, 2008). "This indicates that inhibition of WRN helicase function might have a therapeutic index for the treatment of MSI-H cancer without inducing Werner syndrome related phenotypes." (PMID 30910006, 2019). "Although the direct interaction between XPG and WRN has been suggested to explain the severe developmental defect of XPG/CS patients, unidentified XPG functions were implied based on the greater severity of XPG/CS than Werner syndrome, a premature aging disorder onsets in adulthood." (PMID 24326185, 2014). "Previous DCC studies of Werner syndrome and control cells suggested that DCC defect per se is not sufficient to cause significant genomic instability, but requires absence or dysfunction of "caretaker" genes such as ATR, BRCA1 or WRN." (PMID 21824431, 2011). "Moreover, although theclinical and cellular phenotypes of Werner Syndrome (WS) appear to be distinctfrom that of the otherhuman RecQ helicase disease, it is not clear if WRN has entirely unique or atleast partially overlapping roles with the other RecQ helicases to maintaingenomic stability." (PMID 20157511, 2009).
Bloom syndrome (34 papers, 2007 to 2025). Bloom syndrome (BSyn) is a rare chromosomal breakage syndrome characterized by a marked genetic instability associated with pre- and postnatal growth retardation, facial sun-sensitive telangiectatic erythema, increased susceptibility to infections, and predisposition to cancer. "Mutations in BLM, WRN, and RecQ4 cause Bloom syndrome (BS), Werner syndrome, and Rothmund-Thomson syndrome, respectively." (PMID 27601585, 2016). "Several syndromes are associated to the RecQ genes’ family including Werner syndrome (WS), Bloom syndrome (BS) and Rothmund Thomson syndrome (RTS), that are respectively associated with pathogenic variants in RECQL2/WRN, RECQL3/BLM, and RECQL4 genes." (PMID 31829210, 2019). "While mutational inactivation of WRN and BLM helicases leads to Werner (WS) and Bloom syndromes (BS) respectively, mutations in RecQL4 lead to three autosomal recessive disorders; Rothmund-Thomson syndrome, Baller-Gerold and RAPADILLINO." (PMID 23894508, 2013). "Additionally high T-SCE rates have been observed in cells with deficiencies in WRN and BLM, the genes that are defective in Werner's and Bloom's syndromes, implying a connection to premature aging." (PMID 20952810, 2010). "WRN is a member of the RecQ helicase gene family, and other members of the family include BLM and RTS/RECQL4, which are mutated in Bloom syndrome (BS) and Rothmund–Thomson syndrome (RTS), respectively." (PMID 25688260, 2015). "Inactivation of RecQL2 (WRN), RecQL3 (BLM), and RecQL4 leads to Werner’s syndrome, Bloom syndrome and Rothmund–Thomson syndrome, respectively; these disorders are characterized by genome instability, increased cancer risk and, in the case of Werner syndrome, adult-onset premature aging." (PMID 32085395, 2020). "NSC 19630 targets WRN helicase activity but does not affect other DNA helicases (Bloom syndrome (BLM), Fanconi anemia group J (FANCJ), RECQ1, RecQ, UvrD, or DnaB)." (PMID 27829440, 2016).
breast carcinoma (31 papers, 2010 to 2026). "At present, the polynucleotide polymorphism of the WRN gene has been reported to be closely related to breast cancer in Chinese females, prostate cancer, esophageal cancer and non‐Hodgkin's lymphoma." (PMID 33225619, 2021). "They reported that a WRN specific variant (rs9649886), situated in the C-terminal of WRN, significantly affected breast cancer risk." (PMID 34164337, 2021). "Low WRN mRNA expression in tumors was associated with adverse Breast Cancer Specific Survival (BCSS) in the whole cohort (p = 0.002)." (PMID 26959889, 2016). "A specific mutation (Phe1074Leu) in WRN is found to increase the risk of breast cancer incidence, and dysregulation of WRN expression is observed in breast cancer cells lines." (PMID 26959889, 2016). "Altered Top1 and WRN expression was not only associated with aggressive breast cancers but also correlated with adverse prognostic outcome in patients." (PMID 26959889, 2016). "Drug-induced WRN degradation in breast cancer cell lines was associated with the sensitivity of cells to CPT." (PMID 26959889, 2016). "In contrast, for WRN, low mRNA expression was associated with adverse clinicopathological features and was linked to poor breast cancer specific survival." (PMID 26959889, 2016). "Association of the WRN Cys1367Arg single nucleotide polymorphism (SNP) with breast cancer risk in patient subgroups." (PMID 26690424, 2015). "The SNPs of the WRN gene are associated with different cancers, including bone and soft tissue sarcomas, meningiomas, non‐Hodgkin lymphomas, lung cancer, gastrointestinal neoplasms, breast cancer, and prostate adenocarcinoma." (PMID 40530580, 2025). "Taken together, these novel observations suggest that low WRN expression in human tumors may promote a ‘mutator phenotype’ leading to aggressive breast cancers." (PMID 26959889, 2016). "Interestingly, in patients with estrogen receptor (ER)-positive breast cancers, high WRN and high Top1 levels were associated with a bad prognosis." (PMID 26959889, 2016). "Association of WRN Cys1367Arg genotypes and alleles with breast cancer risk." (PMID 26690424, 2015). "On the other hand, the frequent coding SNP Cys1367Arg in WRN was polymorphic in our study population and could be analyzed for its association with breast cancer risk and onset." (PMID 26690424, 2015). "In patients with breast cancer, methylation status of WRN was significantly correlated with expression and an independent study demonstrated that increased expression of WRN mRNA and protein were associated with improved overall survival (OS) and relapse-free survival (RFS)." (PMID 35782872, 2022). "Hypermethylation of the promoters of tumor suppressor genes ATM, NOTCH1, NUP98, PALB2, TSC2, and WRN had all previously been associated with WTC exposure and were again observed to be hypermethylated in WTC EHC compared to NYUWHS breast cancer patients." (PMID 35564499, 2022). "Even though the potential role of WRN in promoting breast cancer was undetermined, more recently, a novel germline frameshift variant (p.N1370Tfs*23) has been identified in a Chinese family." (PMID 34164337, 2021). "Reported DSB repair variants in breast cancer comprise PALB2, NBN, RAD51, ATM, CHEK2, ATR, RAD50, and WRN." (PMID 31658756, 2019). "In a large clinical cohort of breast cancer patients, we find that WRN and topoisomerase I expression correlate with an aggressive tumor phenotype and poor prognosis." (PMID 26959889, 2016). "The abundance of WRN decreased in CPT-treated sensitive cells; however, WRN remained relatively stable in CPT-resistant breast cancer cells." (PMID 26959889, 2016). "Further we analyzed the expression profiles of WRN and Top1 in a large cohort of human breast cancers to identify any correlations between gene expression and breast cancer specific survival." (PMID 26959889, 2016). "WRN degradation was more extensive in CPT-sensitive breast cancer cells than in CPT-resistant cells." (PMID 26959889, 2016).
breast carcinoma (continued). "Supporting the importance of WRN in cell proliferation after DNA damage, CPT-sensitive breast cancer cells, which displayed drug-induced WRN degradation, showed compromised cell proliferation after CPT treatment." (PMID 26959889, 2016). "Given the essential role of WRN and Top1 in DNA repair and replication we studied their role in breast cancer pathogenesis and prognosis." (PMID 26959889, 2016). "Epigenetic DNA methylation in the promoter region of WRN and a methylation-induced decrease in WRN expression have been found in colorectal, lung, gastric, prostate and breast cancer." (PMID 22797812, 2012). "The mechanism of this activity was not investigated in breast cancer; however, the studies of Shamanna and Opresko revealed some rationale for its consideration, such as camptothecin, and the ability to drive breast cancer cells into senescence in Werner syndrome protein (WRN) dependent manner." (PMID 32640718, 2020). "Additionally we show that in human breast cancers, Top1 and/or WRN expression has prognostic and predictive significance." (PMID 26959889, 2016). "Breast cancer patients with ER-positive tumors expressing high WRN and Top1 had poor survival." (PMID 26959889, 2016). "In the METABRIC (Molecular Taxonomy of Breast Cancer International Consortium) cohort comprising 1977 breast cancers, ~20% of tumors were found to express high Top1 mRNA and ~83% were found to express high WRN mRNA." (PMID 26959889, 2016). "Interestingly, we found that the extent of CPT-induced WRN degradation correlates with increasing sensitivity of breast cancer cells to CPT." (PMID 26959889, 2016). "In the current study, we suggest that CPT-induced WRN degradation in breast cancer cells could be a biomarker for CPT sensitivity." (PMID 26959889, 2016). "To explore this hypothesis, we conducted the first large study of WRN and Top1 expression in human breast cancers." (PMID 26959889, 2016). "Taken together, the pre-clinical data show that WRN and/or Top1 expression could have prognostic and/or predictive significance in breast cancers." (PMID 26959889, 2016). "Top1/WRN expression based stratification could be a promising approach to personalize Top1 inhibitor therapy in breast cancer patients." (PMID 26959889, 2016). "Additionally, mining of breast cancer specific RNAseq data from TCGA, indicated a strong correlation between Top1 and WRN expression (r = 0.325, p = 5.83e-26) suggesting the importance of these two genes in breast cancer." (PMID 26959889, 2016). "The WRN p.Ala616Pro was detectable in the two siblings diagnosed with breast cancer." (PMID 25923920, 2015). "For some genes, single P/LP variants were detected either only in the group of patients with breast cancer (APC, MDM1, MRE11, POLD1, NF1, RAD51C, RECQL4, and WRN) or only in the control group (MCPH1, MSH3, and XPC)." (PMID 39684352, 2024). "To investigate WRN and Top1 expression and the phenomenon of CPT-induced WRN degradation in breast cancer cells, we used three CPT-sensitive (MCF-7, T47D and ZR-75-1) and three CPT-resistant (BT549, MDA-MB-231 and BT-474) cell lines." (PMID 26959889, 2016). "In conclusion, we provide the first pre-clinical evidence that WRN degradation is a biomarker of CPT sensitivity in breast cancer cells, where it can distinguish CPT- sensitive and resistant breast cancer cells." (PMID 26959889, 2016). "Moreover, the loss of function in DNA helicase genes including RECQL, BLM, WRN, RECQL5, and BRIP1 are also known to be highly correlated with the carcinogenesis of breast cancer and the BRCAness phenotype in breast cancer." (PMID 35855837, 2022). "Therefore we investigated the mRNA levels of WRN and Top1 in the METABRIC (Molecular Taxonomy of Breast Cancer International Consortium) cohort." (PMID 26959889, 2016).
breast carcinoma (continued). "Therefore, we analyzed the segregation with breast cancer of the SNVs affecting ERCC6 (p.Ala62Thr) and WRN (p.Ala616Pro) in a family with reported breast cancer affecting three generations (case_574)." (PMID 25923920, 2015).